SPMIP4 (sperm microtubule inner protein 4)
Description:
Microtubule inner protein (MIP) part of the dynein-decorated doublet microtubules (DMTs) in flagellum axoneme. May serve to reinforce and thus stabilize the microtubule structure in the sperm flagella.
Synonyms: C7orf31
Tractability: PROTAC: UniProt records ubiquitination sites on it; ubiquitination databases record sites on it.
Gene: Protein-coding gene on chromosome 7 (25,134,692 to 25,180,356, reverse strand). Ensembl gene ENSG00000153790.
Subcellular location: Cytoplasm, cytoskeleton, microtubule organizing center, centrosome; Cytoplasm, cytoskeleton, flagellum axoneme
Subcellular location (Human Protein Atlas): Mitochondria; Nucleoplasm; Cytosol
Gene Ontology:
Molecular function: protein binding
Cellular component: centrosome
Genetic constraint (gnomAD): Loss-of-function variants: 25 observed, 32.86 expected, observed/expected ratio (o/e) 0.76, 90% interval 0.55 to 1.06. The upper end of that interval is the gene's LOEUF score, 1.06, which puts it in group 4 of 6, group 1 being the genes least tolerant of losing a copy. Missense variants: 617 observed, 641.29 expected, observed/expected ratio (o/e) 0.96, 90% interval 0.9 to 1.03. Synonymous variants: 218 observed, 224.47 expected, observed/expected ratio (o/e) 0.97, 90% interval 0.87 to 1.09.
Homologues: Orthologues: chimpanzee SPMIP4 (98% identical), macaque SPMIP4 (96% identical), dog SPMIP4 (84% identical), pig SPMIP4 (81% identical), rabbit SPMIP4 (75% identical), guinea pig SPMIP4 (75% identical), mouse Spmip4 (74% identical), rat Spmip4 (72% identical), tropical clawed frog spmip4 (32% identical).
Diseases named in the same sentence as SPMIP4 in open-access papers:
SPMIP4 is named in the same sentence as 1 disease in open-access papers, as found by Europe PMC text mining. Sharing a sentence is not in itself a finding about the gene and the disease.
SPMIP4 shares sentences with these, for which no sentence is quoted: glioma (1 paper).